TNF (tumor necrosis factor)
Diseases named in the same sentence as TNF in open-access papers (continued):
Sharing a sentence is not in itself a finding about the gene and the disease.
infection (continued). "Transcriptomics revealed PG-1 treatment broadly tempered infection-induced hyperinflammatory responses, including NF-κB, MAPK, and TNF signaling pathways, and counteracted metabolic reprogramming." (PMID 41295668, 2025). "In TB, upregulation of CCL20 has been observed in response to Mtb antigens, mediated by TNF-α/IFN-γ and the MAPK/NF-κB pathways, suggesting a role in immune cell recruitment during active infection." (PMID 40575568, 2025). "It has been shown that infection upregulates mRNA expression and soluble inflammatory cytokines and chemokines such as type I IFN, TNFα, CCL2, CCL3, RANTES, and IP-10." (PMID 40431705, 2025). "To determine if TBC1D9’s role during hypervirulent infection extends beyond IL-6, we infected epithelial cells with GAS SSI-1 (M3) and measured the expression of IFN-β, TNF-α, IL-1β, and IL-8." (PMID 41306588, 2025). "We also measured inflammatory cytokine levels (TNF-α, IFN-γ, IL-1β, IL-6, IL-10, and IL-12) in the BALF supernatant 3 days post-infection." (PMID 39655914, 2025). "Blocking early TGF-β production during Py17XL infection triggers a rise in IL-10 while simultaneously blocking both TGF-β and IL-10R signalling increases TNF-α and IFN-γ levels, allowing prolonged survival and infection resolution in 40% of these mice." (PMID 39907835, 2025). "Collectively, these results indicate that both TLR4 and SLAMF1 are required for the early induction of TNF mRNA by HMPV in human MDMs, while only SLAMF1 contributes to HMPV-mediated IFNB1 expression at later stages of infection." (PMID 41346628, 2025). "Infection serum can be used to detect antigen-specific antibody concentrations (IgG/IgG1/IgG2a) and cytokines (IFN-γ, IL-2, TNF-α)." (PMID 40733646, 2025). "TLR4 overexpression significantly increased HMPV-stimulated TNF and IFNB1 mRNA levels at later stages of infection." (PMID 41346628, 2025). "Specifically, estradiol alleviates virus-induced immunopathology by downregulating the expression of pro-inflammatory cytokines such as TNF-α, IL-6, and CCL2, thereby mitigating excessive pulmonary inflammation and improving infection outcomes." (PMID 40872527, 2025). "Pro-inflammatory cytokines, such as TNF-α, IL-1β, IL-6, and IFN-γ, are critical in initiating inflammatory reactions and serve as primary mediators of immune responses during infection or injury." (PMID 40364844, 2025). "Modules with increased expression with Th17 priming and RV-16 infection included Interferon, MAP-kinase and TNF Signaling modules, while expression of Cilia structure/function and Metabolism modules were decreased." (PMID 41332562, 2025). "The indispensable roles for innate cytokines during primary infection are well appreciated, but, more importantly, early IL-6 is paramount for the expansion of primed CD4+ T cells and enhances the production of IL-2, TNF, and IFN-γ during secondary infections." (PMID 40279312, 2025). "The studies of cytokines in the hepatocytes adjacent to cysts revealed increases in TGF-β1 (~4-fold), TNF (~7.5-fold), and IFN (~6-fold) along with PSCs infection." (PMID 40072057, 2025). "Cytokine profiling revealed elevated levels of TNF, IL-8, IL-10, and reduced levels of IL-18 and CCL2 in culture supernatants over the time of infection." (PMID 40794782, 2025). "Continued, pronounced SPI-1-dependent assault on the epithelium appears to drive less regulated IEC extrusion in later stages of infection, which is thought to be NLRC4-independent and further exacerbated by TNF." (PMID 41370284, 2025). "IFNγ and TNF, which are produced by CD4+ effector T lymphocytes, are believed to be the main cytokines responsible for macrophage activation at the site of infection in TB." (PMID 40724823, 2025). "Tumor necrosis factor (TNF), IL1, IL-6, IL-8, and other pro- and anti-inflammatory cytokines are released by the body during a natural infection or following vaccination." (PMID 40711280, 2025).
infection (continued). "Results showed elevated levels of pro-inflammatory cytokines such as TNF-α, IL-6, IL-1β, and chemokines CCL5 (RANTES), and IP-10 (CXCL10) after infection with rHPh-TX H5N1." (PMID 40712003, 2025). "After 4T1 cell infection with SFV delivering inflammatory cytokine gene (SFV/IFNγ and SFV/TNFα), the 4T1 cells produced 2.4 μg/mL IFNγ and 23.6 ng/mL TNFα, respectively." (PMID 40547518, 2025). "The results indicated that 24 h post-infection (MOI 1:1), there was a significant increase in the production of TNF-α, IL-1β, and IL-10 compared to that in the control group." (PMID 40005637, 2025). "Further examination of protein levels of inflammatory cytokines (TNF and IL-1β) and chemokines (MCP-1) at day 2 post-infection showed significantly reduced levels of these mediators in TLR7−/− lungs compared to control lungs." (PMID 40162785, 2025). "In the analysis of cytokines in the infected cecum, site of worm insertion, we observed a significant increase in IL-4, IL-10, TNF, and IFN-γ levels 10 days after infection." (PMID 39899646, 2025). "Following PRRSV infection of porcine alveolar macrophages (PAMs), the mRNA levels of M1 polarization-related factors (including IL-6, TNF-α, CD86, and CXCL-10) gradually increased, reaching a peak at 12 h post-infection (hpi) or 24 hpi." (PMID 40732121, 2025). "TNF-α enhances chemokine expression such as CCL2 and CCL5 in lung epithelial cells, which recruit immune cells, such as neutrophils, to the site of infection." (PMID 40872830, 2025). "The infection also compromised blood–brain barrier (BBB) permeability, allowing peripheral inflammatory markers such as IL-6 and TNF-a to enter the brain." (PMID 39860337, 2025). "Upon infection of PBMCs, HIV-1ADA induced significantly higher levels of pro-inflammatory cytokines IL-1α, IL-1β, IL-6 and TNF-α as measured via Luminex assay." (PMID 40313367, 2025). "This agrees with the finding that the upregulation of TNF-α and CCL5 in plasma correlates with pathology during subcutaneous infection of BALB/c mice with VEEV TrD." (PMID 39936916, 2025). "Conversely, after infection, the F1F3 chimera vaccine at both doses promoted mixed cytokine secreting with a strong secretion of the pro-inflammatory IFN-γ and TNF-α and the regulatory IL-10 cytokines." (PMID 40666521, 2025). "Post-infection, CF7066 significantly upregulated the transcriptional expression of inflammatory factors such as CCL4, IL-6, IL-8, and TNF-α, exhibiting the highest mRNA levels." (PMID 40793820, 2025). "IHC analysis revealed a significant increase in the expression of the cytokines TNF-α, IL-2, and IFN-γ in lung tissues of the RV group, suggesting a robust inflammatory response to the infection." (PMID 40266210, 2025). "THP1/PMA macrophages were infected with Lai∆envGFP/G (MOI = 1) in the absence (infection control) or presence of an RT inhibitor (EFV), integrase inhibitor (Ral), and caspase 1/4 inhibitors (zVAD-fmk and VX-765) in the presence of TNFα." (PMID 40920844, 2025). "post-infection, hv-WAD significantly increased the production of TNF-α and IL-1β (p < 0.01) in response to both strains." (PMID 41373747, 2025). "MIR155HG and TNF-a affect the activity of SLE, and the high expressions of them promote the occurrence of such complications as infection, renal damage and cardiac damage, harming the prognosis." (PMID 38699702, 2024). "In this study, TNF and INF levels, measured on day 4 after infection, showed high levels in infected mice receiving the extract." (PMID 38962528, 2024). "Early after infection (day 4 PI), plasma levels of IFN-γ, TNF-α, IL-3, IL-17, IL-1β, and IL-4 were increased in baso IL-18R (−) mice but not in basophil-depleted mice." (PMID 38780542, 2024). "Our results indicate that UL26 prevents STAT phosphorylation during infection and antagonizes transcriptional activation induced by either interferon α (IFNA) or tumor necrosis factor α (TNFα)." (PMID 38768227, 2024).
infection (continued). "In comparison to uninfected mice, the levels of IL-1β, IL-6, IL-12p70, TNF-α, CCL2, CXCL2, GM-CSF, and G-CSF were significantly increased in both PLF and serum after infection." (PMID 38951957, 2024). "MAPK, TNF, NFκB, and IL-17 signaling pathways were overrepresented due to genes with increasing transcript levels during IEC infection." (PMID 38427950, 2024). "Infection of the cornea with ZIKV leads to the synthesis of the IL-1β, TNF-α, CCL5, and CXCL-10 which recruits other cells of the immune system to the cornea and this promotes inflammation and damage to corneal tissue leading to keratitis." (PMID 39795906, 2024). "Subsequently, M1 macrophages produce tumor necrosis factor-alpha (TNF-a), interleukin-1 beta (IL-1β), and reactive oxygen species (ROS) to combat infection, clear foreign substances, and ultimately repair the damage." (PMID 39199705, 2024). "The prepared ODHP-NS-HG reverted the inflammatory effect and suppressed the infection by compromising the levels of COX-2, TNF-α, NF-κB-p105, IL-6, and IL-1β in treated group E comparing to untreated groups." (PMID 38217256, 2024). "The visceral AT of mice infected with the Brazil strain of T. cruzi shows elevated levels of TNF, IFN-γ and IL-1, as well as reduced adiponectin and leptin, as a reflection of the inflammatory profile of the infection." (PMID 38533504, 2024). "Lung macerate supernatants showed an increase in the concentration of IL-6, RANTES and TNF-α in the HIV single infection group compared to the uninfected control animals, as well as the Mtb single infection group." (PMID 38799434, 2024). "In the present study, vaccine-induced TNF-α+ CD4+ and CD8+ T cell responses to the C protein were higher after vaccination than infection." (PMID 39112523, 2024). "Several proinflammatory cytokines are secreted during the adaptive phase, such as TNF-α, IFN-γ, IL-1β, IL-12, and IL-18 which together form an inflammatory response regulating parasite growth and infection outcome." (PMID 38623843, 2024). "To investigate the impact of CASK on cytokine production, we measured the levels of IFN-β, IFN-α, IFN-6, TNF-α, IL-6, IL-1β and IP-10 in the culture supernatant of macrophages at 12 h post-H5N1-IAV (MOI=1) infection." (PMID 39850902, 2024). "By translating these findings into mechanistic mathematical models, we revealed the importance of organ-specific immune responses, particularly the requirement of TNF-α and IFN-γ to control infection within the salivary glands." (PMID 39150988, 2024). "Infection with BRSV leads to an increase in several cytokines and chemokines in circulation, including IL-6, TNF-α, IL-18, chemokine-x-c motif ligand (CXCL8), CCL2, CCL3, and CCL5, mediating the subsequent influx of leukocytes, predominantly neutrophils." (PMID 39599867, 2024). "Post-infection treatment with varying OMT doses revealed a distinct modulation pattern of IFN-α, IFN-β, IL-6, and TNF-α levels, indicating effects shaping the antiviral immune response." (PMID 38731436, 2024). "During blood-stage infection, pro-inflammatory cytokines such as IFN-γ, TNF-α, IL-6 and IL-8 are crucial for controlling the growth of parasites." (PMID 38689233, 2024). "Spatial host gene expression near infection sites in lungs of top 100 genes in pathways such as MAPK, JAK-STAT, TGF-β and TNF-α were compared." (PMID 38997518, 2024). "In this study, we found that murine B. abortus 2308 infection increases IFN-γ, IL-6, IL-12, and TNF-α." (PMID 38794208, 2024). "During in vivo infection, pigs infected with highly virulent strains of ASFV exhibit elevated systemic production of IFN, TNF-α, IL-1α, IL-1β, and IL-6, mainly facilitated by NF-κB or alternative transcription factors." (PMID 38846950, 2024). "E2 treatment post-infection significantly decreased the mRNA expression of inflammatory genes IL-1β, IL8, IL6 and TNF-α compared to the E. coli infected group (P < 0.05)." (PMID 39600797, 2024).
infection (continued). "Because TNF-α inhibits astrocytic glutamate uptake and increases reactive oxygen species (ROS), characterizing HIV-1-associated effects on this measure would enable elucidation of additional mechanisms by which these cells become dysfunctional in infection and may be restored with MJN110." (PMID 38835765, 2024). "During infection, ATF3 actively adjusts innate immunity by enhancing the expression of TNF-α, IL-1β, and IFN-γ, thereby facilitating bacterial clearance." (PMID 38255898, 2024). "The serum levels of TNFα and IFN-γ were relatively lower in Lysm-cre/Fam96afl/fl mice compared to the control group 4 days post-infection." (PMID 38713713, 2024). "The sensitive strain showed a significant difference between 24 and 48 hr post-infection in pro-inflammatory cytokines, including IFN-γ (rank of difference: -2.33; P=0.05) and TNF-α (rank of difference: -3.86; P=0.002)." (PMID 38800030, 2024). "Upon infection, neutrophils release IL-1 and chemokines (e.g., MCP-1, IP-10, and MIP-1a/β) and pro-inflammatory cytokines (TNF-α and IFN-γ); this results in immune cell recruitment and activation." (PMID 39650648, 2024). "MIR155HG and TNF-α affect the activity of SLE, and the high expressions of them promote the occurrence of such complications as infection, renal damage and cardiac damage, harming the prognosis." (PMID 38699702, 2024). "By producing pro-inflammatory cytokines, including tumor necrosis factor alpha (TNF-α), interleukin-1β (IL-1β), and IL-6, they can also fight off infection." (PMID 38425646, 2024). "Significantly higher maternal levels of TNFα and CD62P were observed in vaccinated individuals with SARS-CoV-2 BTI compared with unvaccinated individuals with infection (p<0.05)." (PMID 39845965, 2024). "One study found that infection with Trichinella pseudospiralis in EAE mice led to reduced levels of IL-1β, TNF, and IL-17 in both their spinal cord and splenocytes." (PMID 38250940, 2024). "INFγ, TNFα, and IL-17-positive CD4+ T cells population only increased at an early stage of infection by WT and CNA25 suggesting their role in fungal clearance and early immune activation (Fig. 7Aiii,iv,v)." (PMID 38783167, 2024). "Reduced TNF-α production results from lower levels of miR-125b, which lowers the TNF-α production, reducing the host's ability to combat the infection." (PMID 39176271, 2024). "After the infection at a concentration of 9 conidia per cell with fixed and swollen AF293 conidia for 10 hours, the supernatants were collected and analyzed for TNF-alpha expression." (PMID 38979340, 2024). "Compared with infection alone, levamisole and BMS-1 reduced IL-1β, IL-10, IL-18, TNF-α and IFN-γ mRNA expression and increased IL-2 and IL-8 mRNA expression (P < 0.01)." (PMID 39075562, 2024). "In the control macrophages, infection by both Mtb HN878 and CDC1551 upregulated the percentage of TNF-α + and IL-1β + cells (middle and right columns)." (PMID 38980014, 2024). "The results indicated that the transcript levels of TNF-α, IL-8, and MMP-9 in the brain tissues of mice infected with ΔzmpC were significantly lower than those of the wild-type strain at 12 h post-infection." (PMID 39080654, 2024). "Within hours after infection with T. gondii, NK cells release distinct cytokines IFN‐γ and TNF‐α that limit the further expansion of parasites from primary sites to other places." (PMID 39031850, 2024). "At 5 days after inoculation, the mRNA expression levels of TNF-α, IL-12, and CXCLi1 were more significantly increased (p < 0.01), and the increased expression of IL-1β and IFN-γ was also observed at 5 days post-infection (p < 0.05)." (PMID 38846788, 2024). "Infection of BRB with ZIKV leads to the generation of IL-1β, IL-6, IFN-α, IFN-β, TNF-α, CCL5 and CXCL-10." (PMID 39795906, 2024).
infection (continued). "After the piglets were challenged with G. parasuis for 48 h, the IL-1β, IL-10, IL-18, TNF-α and IFN-γ mRNA expression levels in the blood of the infection group were significantly greater than those in the blood of the control group (p < 0.01)." (PMID 39075542, 2024). "In vivo experiments in mice of catheter-induced S. aureus infection showed a significant reduction in cytokine secretion of IL-1β, TNF-α, CXCL2, and CCL2 during biofilm infection." (PMID 38571946, 2024). "IL-12 and IL-18 transcripts were maintained relatively low level in PEDV CV777-infected cells; in contrast, infection of IPEC-J2 with PEDV for 48 h and 72 h induced a sharp increase of TNF-α and IL-8 transcripts." (PMID 39104852, 2024). "Thus, changes in TNF-α production may be required to establish and maintain long-term infection." (PMID 38533492, 2024). "In order to investigate the role of JTY_0672 in the inflammatory response, we considered the colonization data from organs, and measured the levels of IL-1β, IL-6, TNF-α, and INF-γ in the sera of mice on day 7 after infection." (PMID 39845031, 2024). "In this study, we found that infection of RAW 264.7 macrophages with L. plantarum induced PI3K/Akt expression, but only mildly induced TNF-α and iNOS activation was negligible in the presence of these bacteria when compared to DSV." (PMID 39338507, 2024). "We found that rBCG-Rv1002c infection of macrophages activated the T cell response, prompting T cells to significantly secrete IFN-γ and TNF-α." (PMID 38932351, 2024). "Pro-inflammatory cytokines play a key role in the host immune response to infection and they include IL-1β, IL-8, IL-12, IL-17, IFN-γ, and TNF-α." (PMID 38543749, 2024). "While it is essential for infection clearance, the uncontrolled release of mediators like IL, IFN, and TNF can be detrimental." (PMID 39066369, 2024). "However, it is important to note that this line of reasoning may not extend to other causative pathogens of craniotomy infection, which could be exacerbated by TNF depletion and remains to be assessed." (PMID 39044282, 2024). "Concentrations of C-reactive protein (CRP), procalcitonin (PCT), interleukin-6 (IL-6), and tumor necrosis factor-alpha (TNF-α) in plasma and bronchoalveolar lavage fluid (BALF) measured at 6 h after infection were notably higher than those at 54 h." (PMID 38323827, 2024). "During the infection an important increase of cytokines like IL-6, interferon γ (IFN-γ) and Tumor Necrosis Factor alpha (TNF α) had been documented." (PMID 37500944, 2024). "In vitro, CrT1 function (Na+-dependent 14C-Cr uptake), expression and promoter activity significantly decreased following TNFα/IL1β treatments and AIEC infection." (PMID 38928243, 2024). "During PKDL, there is an increase in the production of Th1-cell-specific cytokines, namely IFN-γ, TNF-α and IL-12, as well as IL-17A, IL17F and IL22 specific to Th17 cells show a protective role during infection." (PMID 39587036, 2024). "Rather, CD4 T cells eventually control infection in the SG through the production of the cytokines interferon (IFN)-γ and tumour necrosis factor (TNF)-α, which inhibit viral replication." (PMID 39150988, 2024). "Similar to the findings in our transcriptional analysis, we found increased TNFα (P = 0.028) and CXCL1 (P = 0.0056) in the ECRG4 KO mouse infection, as well as a trend towards increased CXCL2, IL1β, and IL6." (PMID 39509414, 2024). "The analysis revealed that the frequencies of IFNα- and TNF-producing pDC decreased over time in the CHHIL participants and, at two years post-infection, frequencies approached those seen in HW+ Flores residents, except for one outlying CHHIL donor (D1)." (PMID 39013877, 2024). "We observed significantly higher levels of IL-6 and TNF-α in both serum and lungs of DDX5+/- mice than that in DDX5+/+ mice following infection with P. multocida and S. aureus for 0–12 h, and M. pneumoniae for 0–24 h." (PMID 38182816, 2024).